C5 (complement C5)
Diseases named in the same sentence as C5 in open-access papers (continued):
Sharing a sentence is not in itself a finding about the gene and the disease.
Thrombocytopenia (5 papers, 2017 to 2025). A reduction in the number of circulating thrombocytes. "C5-deficient mice were protected from lethal thrombosis and had milder thrombocytopenia, consumptive coagulopathy, and liver injury with embolism and lower PLA production than C5-sufficient mice." (PMID 28205538, 2017). "Severe thrombocytopenia in Group-PS (6.5 x 104/μL) was significantly ameliorated by Anti-C5 administration (38.6 x 104/μL, P <0.01), and the inter-group difference was more pronounced in the long-term." (PMID 37398677, 2023). "SAA cannot prevent the thrombocytopenia caused by LPS-induced DIC, which indicated that complement activation upstream of C5 contributed to platelet clearance." (PMID 36127691, 2022). "It is possible, however, that the C5 inhibition may have been acting on co-existent idiopathic thrombocytopenia rather than on aβ2GPI induced thrombocytopenia." (PMID 31471128, 2020).
uveitis (5 papers, 2016 to 2021). An inflammatory process affecting a part of or the entire uvea. "It is also possible that epistatic effects of variants in other genes within the complement system (i.e., C5) may contribute further to uveitis susceptibility." (PMID 28408754, 2017). "Of interest is that anti-C5 therapy has been shown to alleviate the severity of disease in mouse models of experimental induced uveitis." (PMID 26934706, 2016). "The TRAF1/C5 variants are located near genes encoding for the complement component 5 and the TNF-receptor associated factor 1, a negative regulator of the TNF pathway, underscoring the role of TNF signaling in JIA associated uveitis." (PMID 34438537, 2021).
acute respiratory distress syndrome (4 papers, 2021 to 2024). Progressive and life-threatening pulmonary distress in the absence of an underlying pulmonary condition, usually following major trauma or surgery. "In addition, SARS-CoV-2 acts as a complement activator in a host so that C3 and C5 are activated, and ultimately induce acute respiratory distress syndrome (ARDS) in a host." (PMID 36289895, 2022).
Candida infection (4 papers, 2011 to 2025). "Remarkably, even during systemic infection, phagocyte-derived C5, in addition to liver-derived C5, played a crucial role in fungal clearance and protection during systemic candidiasis." (PMID 39918335, 2025). "Our observation that the C5aR−/− mice recapitulate the cardiac phenotype characterized by reactivation of the fetal gene expression, Rgs2 down-regulation and sensitivity to Candida infection and isoproterenol administration, reveals the first step in the mechanism of the C5 effect." (PMID 21829669, 2011).
cerebral malaria (4 papers, 2008 to 2021). A sequestration of Plasmodium falciparum in the brain, which can cause coma and/or seizures. "C5 deficiency is protective against cerebral malaria development." (PMID 34408631, 2021). "In cerebral malaria, C1q and C5 levels have been found to be increased in mice studies while another murine study also points to the requirement of MAC in the pathogenesis of cerebral malaria." (PMID 23843682, 2013). "C1q and C5 are locally upregulated in the brain in cerebral malaria." (PMID 34408631, 2021). "Protection of C5 deficient mice against cerebral malaria is mediated through the inhibition of MAC formation, not through C5a-induced inflammation." (PMID 34408631, 2021). "Murine models have also highlighted a possible role for C5a in cerebral malaria as C5 deficient mice or those treated with antibodies blocking C5a and its receptor respectively did not develop and could be rescued from cerebral malaria." (PMID 34168652, 2021). "The current study was conducted to analyze complement factors C1q, C3 and C5 – catalyzing crucial steps in the complement cascade – in the brains and sera of mice infected with Plasmodium berghei ANKA – a well-established model of cerebral malaria." (PMID 18847493, 2008).
dysferlinopathy (4 papers, 2022 to 2024). "However, the deposition of diffuse myofiber complement C5b‐9 complex in muscle biopsies stands as a distinctive pathological hallmark of dysferlinopathy." (PMID 39350328, 2024). "Since complement pathways contribute to disease progression in dysferlinopathy, C3 and C5 serum levels were evaluated in BlAJ at 6 and 12 months vs 12 m BlAJ+ONX." (PMID 36402750, 2022). "Compared to calpainopathy, Becker muscular dystrophy, and inflammatory myopathies, the unique profile of minimal inflammatory cell infiltrates, absent to focal MHC class I, and diffuse myofiber complement C5b-9 deposition is the pathologic signature of dysferlinopathy muscle biopsies." (PMID 35135626, 2022).
influenza (4 papers, 2013 to 2025). An acute viral infection of the respiratory tract, occurring in isolated cases, in epidemics, or in pandemics; it is caused by serologically different strains of viruses (influenzaviruses) designated A, B, and C, has a 3-day incubation period, and usually lasts for 3 to 10 days. "CD103+ DC, a migratory DC subset, can secrete complements C3 and C5, resulting in the induction of T-cell immune responses and virus clearance after influenza infection." (PMID 39221016, 2024). "Since only CD103+ DCs showed increased C3 and C5 mRNA expression upon influenza infection, we evaluated the contribution of CD103+ DCs to the observed increase in C3a and C5a levels in the lung during influenza infection." (PMID 23326231, 2013). "The specific production of C3 and C5 by CD103+ DCs underlines their central role in transporting antigen from the lung to the dLN, allowing the priming of T-cells during the early phase of influenza infection." (PMID 23326231, 2013). "No modulation of C3 and C5 mRNA expression was observed in CD11b+ DCs after influenza infection." (PMID 23326231, 2013).
membranous nephropathy (4 papers, 2019 to 2025). "Our results suggest a potential benefit of the use of eculizumab (a monoclonal anti-C5) in membranous nephropathy." (PMID 32083137, 2019). "Furthermore, anti-C5 therapy was tested in membranous nephropathy but failed to reduce proteinuria." (PMID 40519165, 2025).
psychosis (4 papers, 2019 to 2024). "In the few studies on the complement levels of patients with psychosis, most of the results focused on complement C3 and C4, while there are few studies on the role of complement C5 in psychosis, and most of them are insignificant findings." (PMID 36631451, 2023). "Considering that the complement system plays a role in synapse elimination/pruning, which may be involved in the pathogenesis of psychosis, C5 levels may be altered during the development of psychosis." (PMID 36631451, 2023). "Compared to the insignificant difference found in the inflammatory factors, the complement factors showed more significant differences between CHR individuals and HC, and lower levels of C5 and C5a in CHR individuals were associated with a higher risk of conversion to psychosis." (PMID 36631451, 2023). "Therefore, alterations in serum complement levels, particularly C5 and C5a, may precede the first episode of psychosis in individuals with CHR." (PMID 38868725, 2023).
schizophrenia (4 papers, 2021 to 2024). A major psychotic disorder characterized by abnormalities in the perception or expression of reality. "Accompanying the metabolic disruption identified in patients with schizophrenia was an increase in several complement effector proteins, including C4a/b, C5, C6, C8a, and C9." (PMID 34741130, 2022). "Elevated C4 levels have simultaneously been found in the CSF of patients with schizophrenia, and another report further found elevations of C5 in the CSF of patients with this disorder, while the blood leukocyte fraction from drug-free FEP showed no change in C4 mRNA." (PMID 34063598, 2021). "Moreover, the C5 protein levels in the CSF were elevated in patients with schizophrenia." (PMID 34063598, 2021).
staphylococcus aureus infection (4 papers, 2021 to 2025). An infectious process in which the bacteria Staphylococcus aureus is present. "The C5 and IAPP genes are predicted to be involved in neuroactive ligand-receptor interaction, Staphylococcus aureus infection, Pertussis, complement, and coagulation cascades." (PMID 34262595, 2021).
allergic asthma (3 papers, 2006 to 2025). A asthma with a basis in a pathological type I hypersensitivity reaction. "The complement C3- and C5-derived anaphylatoxins C3a and C5a are known to contribute to the development of allergic asthma through their impact on dendritic cells and ILC2." (PMID 41148813, 2025). "Genetic ablation or pharmacological targeting of C5 or C5aR1 during allergen sensitization resulted in aggravation of the allergic asthma phenotype, suggesting that C5aR1 protects from the development of allergic asthma." (PMID 28231307, 2017). "In murine models of HDM-induced allergic asthma, elevated C5a levels in bronchoalveolar lavage (BAL) fluid correlate with Th2 cell differentiation and airway hyper-responsiveness (AHR), which are attenuated by C5 blockade." (PMID 41148813, 2025).
Autoimmunity (3 papers, 2019 to 2023). The occurrence of an immune reaction against the organism's own cells or tissues. "C5 has a potential role in both: C5 deficiency increases susceptibility of A/J mice to many infectious agents and C5 function and dysfunction are indicated in immunity and autoimmunity." (PMID 31601172, 2019).
dengue (3 papers, 2020 to 2022). "Our data also indicate that the levels of C2, C4b, C5, C5a, C9, factor D and factor I are significantly associated with clinical parameters, especially with platelet counts, of dengue patients." (PMID 32913345, 2020). "Because the vasculopathy in dengue is mainly due to excessive release of C3a and C5a, the potential use of anti-C5 mAb may likely reduce vascular leakage and associated complications in severe dengue." (PMID 35874775, 2022). "In dengue patients, C2 levels correlated with the levels of C4b, C5, C5a and factor D (Spearman’s rho = 0.5, 0.39, 0.61, − 0.25; P < 0.0001, < 0.0001, < 0.0001 and = 0.0002, respectively)." (PMID 32913345, 2020). "C2, C5, and C5a levels were significantly increased in dengue patients compared to controls and are highest in DWS patients, indicating that the complement system is strongly activated in order to respond to DENV infection." (PMID 32913345, 2020). "The levels of C2, C5, and C5a were significantly higher in dengue and DWS patients compared to those in healthy controls (P < 0.0001) and also higher in DWS patients compared to those in dengue patients (P = 0.018, < 0.0001 and 0.049, respectively)." (PMID 32913345, 2020). "The levels of complement factors C2, C5, and C5a were higher in dengue and dengue with warning signs (DWS) patients compared to those in healthy controls, while factor D levels were decreased in dengue and DWS patients compared to the levels determined in healthy controls." (PMID 32913345, 2020).
dermatomyositis (3 papers, 2018 to 2023). Dermatomyositis (DM) is a type of idiopathic inflammatory myopathy characterized by evocative skin lesions and symmetrical proximal muscle weakness. "Gefurulimab (mAbID 1253), a bispecific VH-VH mAb that binds to C5 (to inhibit complement cascade) and albumin (to extend antibody half-life), are currently under clinical development for the treatment of gMG, along with dermatomyositis and proteinuria." (PMID 38140161, 2023).
endocarditis (3 papers, 2019 to 2021). Inflammation of the endocardium. "While complement C5 is required for disease progression in the joints, endocarditis depends on Fc receptors and is independent of C5." (PMID 30858306, 2019).
glioma (3 papers, 2021 to 2024). A benign or malignant brain and spinal cord tumor that arises from glial cells (astrocytes, oligodendrocytes, ependymal cells). "We divided the glioma samples into different immune subtypes (C1–C6 subtypes) and found that the high-risk group had significantly more C4 and less C5 immune subtypes than the low-risk group in all three cohorts." (PMID 38540734, 2024). "A previous study carried out by the same group reported that C5/C5a released from glioma-associated microglia binds to the C5a receptor (C5aR) on glioma cells and induces TMZ-resistance by elevating the expression of DNA damage repair (DDR)-related proteins (Molecular event 14)." (PMID 36555253, 2022). "For instance, IFNγ stabilises Irf8 activation in glioma cells and microglial C5/C5a complement component induced TMZ resistance." (PMID 36555253, 2022). "A number of complement molecules like C1q, C5, and C3 are highly expressed in glioma cells, and are secreted into the microenvironment to participate in polarization of TAM, recruitment of peripheral monocyte and neoangiogenesis." (PMID 33869223, 2021).
Hypertension (3 papers, 2022 to 2024). The presence of chronic increased pressure in the systemic arterial system. "Elevated serum C3 and C5 levels in hypertensive patients and animal models of hypertension provide another hint of the role of the complement system in the etiology of hypertension." (PMID 35354938, 2022).
Insulin resistance (3 papers, 2017 to 2022). Increased resistance towards insulin, that is, diminished effectiveness of insulin in reducing blood glucose levels. "Intact C3 and C5 proteins and the cleaved C3a and C5a peptides are reported to act as mediators of inflammation-induced insulin resistance, but a beneficial effect of complement factor D, a protease required for the generation of the C3 convertase, on β-cell function has been demonstrated." (PMID 28921001, 2018). "Insulin resistance (HOMA-IR) positively correlated with iC3b and factor H in PCOS and controls; additionally, in controls, properdin, C3a, C3d, factor I, factor B, C5a, C5b,6 complex and C5 all positively correlated with HOMA-IR." (PMID 36293087, 2022).
ischemic heart disease (3 papers, 2009 to 2024). "Eculizumab, a monoclonal C5-antibody, is currently being used to treat paroxysmal nocturnal hematuria, and pexelizumab, also a C5-antibody, has been studied as adjunctive therapy in ischemic heart disease." (PMID 20150958, 2009).
ischemic stroke (3 papers, 2019 to 2022). A stroke disorder caused by obstruction of blood flow to the brain, due to thrombotic (local blood clot formation) or embolic (due to a blood clot or other material traveling from another site) event. "Therefore, focal or temporal C5 inhibition during the peri-ischemic time period, instead of lifelong C5 deficiency, could be a better option for reducing the C5-mediated detrimental effects after ischemic stroke." (PMID 31011487, 2019). "However, the effect of anti-C5 monoclonal antibodies and C5aR1 antagonists in ischemic stroke is limited." (PMID 31011487, 2019).
liver steatosis (3 papers, 2019 to 2023). "Notably, C5 deficiency had little effect on the development of liver steatosis and the expression of Gly-tRF in AFLD mice." (PMID 31076642, 2019).
Lung Injury (3 papers, 2013 to 2021). "The anaphylatoxin C5a, a potent immune modulator released from C5 cleavage during complement activation, promotes the recruitment and activation of neutrophils during lung inflammation, which results in acute lung injury and ARDS." (PMID 34868021, 2021). "Surprisingly, C3−/− mice developed the full intensity of acute lung injury (ALI) in a C5a-dependent manner due to the action of thrombin that generates C5a directly from C5." (PMID 26420913, 2015).
lymphoma (3 papers, 2018 to 2025). A malignant (clonal) proliferation of B- lymphocytes or T- lymphocytes which involves the lymph nodes, bone marrow and/or extranodal sites. "He underwent kidney transplantation four years after initiating C5 inhibitor therapy and passed away at 16 years of age from a post-transplant lymphoma." (PMID 40224677, 2025).
membranoproliferative glomerulonephritis (3 papers, 2017 to 2024). Inflammation of the glomeruli characterized by deposits at the intraglomerular mesangium, resulting in thickening of the glomerular basement membrane, activation of complement, and impaired kidney function secondary to damaged glomeruli. "For example, targeting C5 with the neutralizing antibody Eculizumab in humans has proved effective in controlling disease severity and progression in patients with PNH, aHUS, membranoproliferative glomerulonephritis, and antiphospholipid syndrome." (PMID 28932227, 2017).
renal fibrosis (3 papers, 2022 to 2025). A final common manifestation of a wide variety of chronic kidney diseases characterized by glomerulosclerosis and tubulointerstitial fibrosis. "Similarly, Masson's Trichrome staining shows similar levels of renal collagen between C5−/− and C5+/+ rats, indicating C5 deletion does not induce renal fibrosis." (PMID 41189475, 2025).
retinal degeneration (3 papers, 2018 to 2024). Degeneration of the retina. "To determine the contribution of these three complement pathways to C5 activation and retina degeneration, we used a mouse deficient in C4 to eliminate CP and MBL pathway activation." (PMID 29743491, 2018). "Our previous study showed that complement components are produced and can be activated in the retina, indicating that intravitreal C5 inhibition could potentially attenuate retinal degeneration." (PMID 37754247, 2023).
acute liver failure (2 papers, 2022 to 2023). Rapid deterioration of liver function causing encephalopathy and coagulopathy. "We also demonstrated that just a single dose of Anti-C5 antibody ameliorates not only hepatic ischemia/reperfusion injury but also fulminant hepatitis/acute liver failure in murine models, dominantly via the C5a-mediated cascade." (PMID 37398677, 2023). "An anti-C5 antibody was effective at treating concanavalin A-induced acute liver failure (ALF) in mice." (PMID 35677590, 2022).
acute lung injury (2 papers, 2013 to 2021). A condition of lung damage that is characterized by bilateral pulmonary infiltrates (pulmonary edema) rich in neutrophils, and in the absence of clinical heart failure. "Here, we examined the effect of LTB4 binding on structure and function of OmCI and investigated the relative importance of C-mediated C5 activation and LTB4 in a mouse model of immune complex-induced acute lung injury (IC-ALI)." (PMID 23625922, 2013). "Here, we examined the effect of LTB4 binding on OmCI structure and function and investigated the relative importance of C-mediated C5 activation and LTB4 in a mouse model of immune complex-induced acute lung injury (IC-ALI)." (PMID 23625922, 2013).
acute pancreatitis (2 papers, 2013 to 2024). An acute inflammatory process that leads to necrosis of the pancreatic parenchyma. "The proposal is also supported by the observation that inflammation cannot be inhibited in a mutant mouse deficient in C5 expression with acute pancreatitis and associated lung injury." (PMID 24063402, 2013).
airway hyperresponsiveness (2 papers, 2006 to 2017). "Further, C5 or C5aR1 targeting is associated with increased airway hyperresponsiveness." (PMID 28231307, 2017).
anti-neutrophil cytoplasmic antibody-associated vasculitis (2 papers, 2021 to 2024). Group of systemic vasculitis with a strong association with anca. "The C5 blocking monoclonal antibody (mAb) eculizumab has been successfully used for PNH for >10 years and a specific C5aR1 antagonist (avacopan) has been filed for Food and Drug Administration approval for the treatment of antineutrophil cytoplasmic antibody-associated vasculitis." (PMID 34099640, 2021).
aspergillosis (2 papers, 2022 to 2023). Aspergillosis is an infection, growth, or allergic response caused by the Aspergillus fungus. "An earlier study noted a higher degree of lethality in a systemic model of aspergillosis in DBA/2N mice lacking complement C5, compared to complement sufficient outbred CFW mice." (PMID 36211424, 2022).